CASP8 (caspase 8)
Diseases named in the same sentence as CASP8 in open-access papers (continued):
Sharing a sentence is not in itself a finding about the gene and the disease.
basal cell carcinoma (6 papers, 2016 to 2024). A carcinoma involving the basal cells. "Transcriptional and splicing anomalies have been observed in intron 8 of the CASP8 gene (encoding procaspase-8) in association with cutaneous basal-cell carcinoma (BCC) and linked to a germline SNP rs700635." (PMID 26740556, 2016).
enteritis (6 papers, 2018 to 2024). Inflammation of the small intestine. "Similarly, the deficiency of intestinal epithelial caspase-8 signaling induced necroptosis-mediated enteritis and high lethality after Salmonella Typhimurium infection." (PMID 39840043, 2024). "Previous studies have shown that caspase-8 could cleave RIPK3 to inhibit necroptosis of IECs during the process of enteritis caused by Salmonella, thereby playing a role in maintaining the intestinal barrier function and limiting the colonization of pathogens." (PMID 35110556, 2022). "In CASP8-deficient mice, STAT1 activation in epithelium aggravated the sensibility toward bacterial-induced enteritis, intestinal inflammation, and lethality." (PMID 35795789, 2022). "To study the role of STAT1 upstream of Caspase-8 during gastrointestinal infection we subjected control, Casp8ΔIEC mice and Casp8ΔIECxStat1−/− mice to the streptomycin mouse model for Salmonella Typhimurium induced enteritis." (PMID 34497340, 2022). "Mice lacking Caspase-8 in the intestinal epithelium are highly sensitive towards bacterial induced enteritis and intestinal inflammation, resulting in an enhanced lethality of these mice." (PMID 34497340, 2022).
fibrosarcoma (6 papers, 2009 to 2023). A malignant mesenchymal fibroblastic neoplasm affecting the soft tissue and bone. "Cleaved cFLIP then allows a more efficient recruitment of TRAF1/2, the 'receptor-interacting protein' (RIP1) and the the 'rapidly growing fibrosarcoma or rat fibrosarcoma-1' (Raf-1) protein to the cFLIP-caspase-8 heterodimer." (PMID 21477291, 2011). "Interaction of FADD and caspase-8 with TNFR signalling proteins is an essential feature in transformed fibrosarcoma cells on TNF stimulation." (PMID 19826422, 2009). "In this context, it has been reported recently that apoptosis induction after transduction of HT-1080 human fibrosarcoma cells with an oncolytic adenovirus, expressing a short hairpin RNA against Apollon, was mediated by the proteolytic activation of caspase-8 and caspase-3." (PMID 19223905, 2009).
gastric adenocarcinoma (6 papers, 2010 to 2025). "Cross-linking of DAF isoform with its antibody in human stomach adenocarcinoma cells elevated the expression of caspase-3 and caspase-8, and activated caspase-3." (PMID 20380727, 2010). "In our study, we demonstrate that GSK3 inhibitors could sensitize certain gastric adenocarcinoma cells to TRAIL-induced apoptosis by increasing caspase-8 activity and its downstream signal transmission." (PMID 30557366, 2018). "In summary, we show that GSK-3 inhibitors sensitize gastric adenocarcinoma cells but not primary gastric epithelial cells to TRAIL-induced apoptosis by inducing caspase-8 activation through mitochondrial pathway." (PMID 30557366, 2018). "Both inhibitors can sensitize gastric adenocarcinoma cells, but not primary gastric epithelial cells, to TRAIL-induced apoptosis by increasing caspase-8 activity and its downstream signal transmission." (PMID 30557366, 2018).
HCMV infection (6 papers, 2017 to 2025). "The first five genes are members of the pathways in cancer, among which CASP8, STAT3 and MAPK1 are related to viral carcinogenesis, including Kaposi’s sarcoma-associated herpesvirus and human cytomegalovirus (HCMV) infection." (PMID 40768543, 2025). "Surprisingly, we found little change in the abundance of cFLIPS in monocytes following HCMV infection, suggesting a minimal role for cFLIPS in preventing caspase-8 activation." (PMID 41190811, 2025). "To elucidate how procaspase-8 cleavage is blocked during HCMV infection of monocytes, we first examined the protein levels of cFLIP, a known cellular repressor of caspase-8." (PMID 41190811, 2025). "Moreover, CASP8 could inhibit NK cell proliferation in a murine model of cytomegalovirus infection." (PMID 35928267, 2022). "Equally important, we show for the first time that a non-canonical pathway has evolved in response to HCMV infection, leading to inflammasome-independent maturation of IL-1β via caspase-8 activation." (PMID 30332797, 2018). "Lastly, we demonstrate that HCMV infection of HFFs triggers a non-canonical IL-1β activation pathway where caspase-8 promotes IL-1β maturation independently of caspase-1." (PMID 30332797, 2018). "cFLIPL-mediated inhibition of caspase-8 and the simultaneous activation of TLR3, but not TNFR1 or TLR4, is required for RIPK3 activation following HCMV infection of monocytes." (PMID 41190811, 2025).
influenza (6 papers, 2021 to 2026). An acute viral infection of the respiratory tract, occurring in isolated cases, in epidemics, or in pandemics; it is caused by serologically different strains of viruses (influenzaviruses) designated A, B, and C, has a 3-day incubation period, and usually lasts for 3 to 10 days. "Simultaneous activation of multiple cell death pathways involving RIPK3 and caspase-8/caspase-1 is proposed to occur during infection by a number of pathogens including Legionella, Francisella, influenza, and Yersinia." (PMID 39058785, 2024). "In BAL fluid from macaques with lethal influenza, only irrelevant caspase-8 cleavage byproducts were detected." (PMID 35271686, 2022). "Caspases CASP3, CASP8, CASP10, and FAS associated death domain (FADD) are important for apoptosis which is a pathway downregulated upon influenza vaccination." (PMID 34695164, 2021). "Moreover, Z-DNA-binding protein 1 (ZBP1), a novel effector of necroptosis, triggers NLRP3 inflammasome activation and release of IL-1β through the RIPK1-RIPK3-Caspase-8 axis during influenza A virus (IAV) infection." (PMID 36619743, 2022). "Unlike shown here for SARS-CoV-2, influenza pathogenicity is mainly driven by inflammasome pathways and GSDMD104, with caspase-8 actually exerting an anti-inflammatory effect." (PMID 41233351, 2025).
liver fibrosis (6 papers, 2014 to 2025). "RIPK3 deficiency alleviated liver fibrosis in a caspase-8-dependent manner by regulating JNK signaling pathway." (PMID 36114543, 2022). "Interestingly, the predicted target gene of rs6726823, CASP8, has been functionally implicated in hepatic stellate cell homeostasis and liver fibrosis in MASLD mouse models." (PMID 41282202, 2025). "As a consequence, ROS production was lower, leading to a reduction in the progression of liver fibrosis in Casp8−/− livers." (PMID 40034259, 2025). "Network pharmacology analysis identified BCL2, CASP3, and CASP8 as major targets of β-sitosterol in liver fibrosis management." (PMID 38461449, 2024). "RIP3 mediates liver injury, inflammation, induction of hepatic progenitor cells/activated cholangiocytes, and liver fibrosis through a pathway suppressed by Caspase-8." (PMID 24963148, 2014). "We have recently shown that Caspase-8-dependent apoptosis but not RIP3-dependent necroptosis promoted liver fibrosis and hepatocarcinogenesis in a model of liver injury caused by conditional deletion of the kinase TGF-β-activated Kinase-1 (Tak1) in parenchymal liver cells." (PMID 24963148, 2014). "Moreover, activation of Caspase-8 inhibits RIP3-dependent liver fibrosis in NASH." (PMID 24963148, 2014). "Taken together, our present study together with previous findings indicate that both programmed cell-death pathways—(Caspase-8-independent) apoptosis and necroptosis—are involved in the pathogenesis of NASH and NASH-induced liver fibrosis." (PMID 24963148, 2014).
myeloid leukemia (6 papers, 2011 to 2023). A clonal proliferation of myeloid cells and their precursors in the bone marrow, peripheral blood, and spleen. "In a human myeloid leukemia cell model, circRNA.0007127 associates with miR-513a-5p or CASP8 to reduce apoptosis by inhibiting CASP8 pathway activation." (PMID 37372440, 2023). "Combining Smac mimetic Birinapant with caspase-8 inhibitor Emricasan can promote necroptosis in myeloid leukemia cells, which may emerge as a promising therapeutic method of AML." (PMID 35330731, 2022). "Moreover, another study found that CPT could sensitize TNF-α-induced apoptosis through ROS-dependent activation of Caspase-8 and p38 in human myeloid leukemia KBM-5 cells." (PMID 28654902, 2017). "The mechanism of Stx-induced apoptosis in the human myeloid leukaemia cell line THP-1 involves the increased expression of DR5 and TRAIL and activation of caspase-8 via a calpain-dependent mechanism through endoplasmic reticulum stress response." (PMID 21858177, 2011).
Parkinson disease (6 papers, 2014 to 2019). A progressive degenerative disorder of the central nervous system characterized by loss of dopamine producing neurons in the substantia nigra and the presence of Lewy bodies in the substantia nigra and locus coeruleus. "Caspase 8 was up-regulated by the HDACis and has been described to regulate neuronal apoptosis involved in neurodegenerative diseases such as Alzheimer’s, Parkinson’s and Huntington’s disease in humans." (PMID 27188386, 2017). "Activation of the TNF-α receptor transduction pathways seems to be of particular relevance for the progression of Parkinson disease by initiating caspase 3 and caspase 8 activation and thereby inducing apoptotic cell death." (PMID 26597538, 2015). "In this study, we have taken advantage of conditional caspase-8 KO mice specifically in the myeloid system to test the in vivo involvement of caspase-8 in microglia activation in animal models of Parkinson's disease." (PMID 26405176, 2015). "Moreover, in Parkinson's disease, Caspase-8 is an effector in apoptotic death of dopaminergic neurons." (PMID 24551850, 2014).
renal cell carcinoma (6 papers, 2015 to 2024). "Collectively, our results suggested that the TP53INP2 inhibited renal cell carcinoma in a way of regulating the caspase-8/TRAF6 apoptotic signaling pathway." (PMID 35615533, 2022). "The inhibition of caspase enzymatic activity by zVAD-fmk in human renal cell carcinoma A498 cells, demonstrated that metformin-induced apoptosis facilitated degradation of the cellular caspase 8 (FLICE)-like inhibitory protein and activated procaspase-8 through a caspase-dependent pathway." (PMID 33537296, 2020). "TIPE2 suppresses TLR4-mediated development of colon cancer by inhibiting caspase-8 activity, while its expression is positively correlated with TNM staging in renal cell carcinoma (RCC) patients." (PMID 25946186, 2015).
retinal ischemia (6 papers, 2015 to 2023). A ischemic disease that involves the retina. "TLR4 can lead to an increased caspase 8 expression in a retinal ischemia-reperfusion model, which is in accordance with our study results." (PMID 32833183, 2021). "Our findings reveal the unique effect of CASP8 on pyroptosis: CASP8 initiates GSDMD-predominant pyroptosis during retinal ischemia, in accordance with the results during pathogen infection." (PMID 32295623, 2020). "As CASP6 or CASP8 inhibition were neuroprotective following retinal ischemia, we tested the effect of these interventions on brain infarction in a thromboembolic model of MCAO." (PMID 26539914, 2015). "Furthermore, we have also reported that caspase-8 (CASP8)-induced NLRP3 promotes IL-1β processing during innate immune responses in an IOP-induced retinal ischemia model." (PMID 32295623, 2020). "A recent study showed that inhibition of caspase-1 reduced IL-1β expression to baseline post retinal ischemia injury, while inhibition of caspase-8 further down-regulated the level of IL-1β, suggesting that IL levels could be regulated by both NLRP3-dependent and other pathways." (PMID 26893104, 2016). "Several papers have reported that caspase-8 activates NLRP3 in human monocytes, intraocular pressure-induced retinal ischemia, and after chemotherapeutic treatment." (PMID 33531049, 2021). "Given these novel findings, we have determined that IL-1β is a central factor enhancing CASP8-HIF-1α signaling to subsequently increase NLRP3/NLRP12/NLRC4 activation and to initiate pyroptosis during retinal ischemia." (PMID 32295623, 2020). "In the present work, we found that inhibition of caspase-8 activation resulted in significant depletion of NLRP3, an observation that agrees with other work indicating a role for caspase-8 in intraocular pressure-induced retinal ischemia." (PMID 33531049, 2021).
Thrombocytopenia (6 papers, 2015 to 2025). A reduction in the number of circulating thrombocytes. "Additionally, we observed transient protection from the thrombocytopenia that arises from lipopolysaccharide (LPS)-induced platelet consumption and clearance when Caspase-8 was deleted in the megakaryocytic lineage." (PMID 33510145, 2021). "Most importantly, mice transplanted with Casp8−/− BM cells developed MDS-like disease within 4 months of transplantation as demonstrated by anemia, thrombocytopenia and myelodysplasia." (PMID 38637559, 2024). "We found that some of the Casp8−/− mice developed MDS-like disease 4 months after the induction of Casp8 deletion as shown by anemia and thrombocytopenia with morphologic dysplasia of blood cells." (PMID 38637559, 2024). "We investigated some apoptotic markers (caspase 3, caspase 8 and BCL2) using the flow cytometry in 60 children with newly diagnosed ITP, 20 children with chemotherapy-related thrombocytopenia (CRT) and 20 healthy children." (PMID 37786823, 2023). "We investigated the effects of the exposure of ABT-737, an apoptosis- and thrombocytopenia-inducing drug, on the expression of FADD and DJ-1 as well as on the caspase-8 activity in human platelets." (PMID 33428668, 2021). "Overall, these data implicate Caspase-8, but not Mlkl, deletion in the megakaryocytic lineage in transient protection from LPS-induced thrombocytopenia." (PMID 33510145, 2021).
thyroid cancer (6 papers, 2009 to 2021). "Promoter methylation status of genes with reported associations in thyroid cancer (CASP8, CDKN2A, DAPK1, ESR1, NIS, RASSF1 and TIMP3) were examined in a cohort of follicular thyroid cancers comprising of 26 Hurthle and 27 Classic subtypes utilizing quantitative methylation-specific PCR." (PMID 27158284, 2015). "Herein, the expression of bax, bcl2, caspase-3 and caspase-8 genes of sw-1736 thyroid cancer cell line was examined after the incubation with 7 μl of the batch curcumin-niosome nanoparticles in 100 μl of cell culture media for 72 h." (PMID 34453618, 2021). "In the thyroid cancers, CASP8, RASSF1, and NIS were methylated in 9/13, 10/13, and 7/13 respectively." (PMID 21738852, 2011). "CASP8, RASSF1 and NIS were also methylated in concurrently present normal thyroid tissue in 3/11, 4/11 and 3/11 matched thyroid cancer cases (matched for presence of both normal thyroid tissue and thyroid cancer), respectively." (PMID 21738852, 2011). "A pilot study by our group which looked at various thyroid lesions (normal thyroid, hyperthyroid, FTC, FTC-Hurthle and PTC) found CASP8, RASSF1and NIS to be frequently methylated in normal thyroid, hyperthyroid lesions, thyroid cancer and their adjacent normal." (PMID 27158284, 2015). "It is reported that IL-32γ and IL-32β induce caspase-8-dependent cell death in HEK293 cells whereas IL-32α does not, and that the treatment of alternative splicing inhibitor results in the predominant expression of IL-32γ splice variants and cell death in thyroid cancer cell lines." (PMID 29050245, 2017).
triple-negative breast carcinoma (6 papers, 2016 to 2025). An invasive breast carcinoma which is negative for expression of estrogen receptor (ER), progesterone receptor (PR), and human epidermal growth factor receptor 2 (HER2). "We demonstrate that loss of PAR-4 in triple negative breast cancer cell lines (TNBC) mediates resistance to DNA damage-induced apoptosis and prevents activation of caspase-8." (PMID 31217499, 2019). "In this study, GN and GO were investigated as carriers of M to a tumor, which has a more organized structure than cell culture and which was cultured from the MDA-MB-231 triple-negative breast cancer cell line by analyzing CASP3 and CASP8 activity, oxidative stress, and expressing cytokine proteins." (PMID 37176095, 2023).
type 2 diabetes (6 papers, 2008 to 2025). "Islets from individuals with type 2 diabetes show elevated markers of apoptosis, such as caspase-3 and caspase-8." (PMID 34822454, 2021). "Casp8 (caspase 8) is essential for ß cell apoptosis in type 1 and type 2 diabetes models and in regulating ß cell mass and insulin secretion under physiological conditions." (PMID 19471607, 2008).
acute kidney injury (5 papers, 2018 to 2024). Sudden and sustained deterioration of the kidney function characterized by decreased glomerular filtration rate, increased serum creatinine or oliguria. "Consistent with our results, the RIP3-mediated activation of the NLRP3 inflammasome was also observed in caspase-8-deficient dendritic cells treated with LPS and acute kidney injury." (PMID 38911926, 2024). "Under LPS and dual hypoxia stimulation, destabilized Pellino1 (Ser39 phosphorylation and turnover) induced by death-associated protein kinase 1 (DAPK1) leads to the release of TRIF-RIP1 signalosome to recruit caspase-8 and induces tubular damage and cell apoptosis in acute kidney injury (AKI) model." (PMID 35197966, 2022). "In septic acute kidney injury (AKI), DAPK1 Peli1 phosphorylation promotes RIP1 binding to caspase-8 and ultimately induces tubular apoptosis." (PMID 38179042, 2023).
chronic myeloid leukemia (5 papers, 2014 to 2024). "In other cancer cells, namely, chronic myeloid leukemia cells, NaB was found to induce apoptosis via the activation of caspase 8 and caspase 9, which are key mediators of the extrinsic and intrinsic apoptotic pathways, respectively." (PMID 39200243, 2024).
fungal infection (5 papers, 2015 to 2020). "WT BMDMs released a significant amount of IL-18 after fungal infection, whereas the Casp1/11–/–Ripk3–/–Casp8–/– BMDMs released significantly less." (PMID 33109609, 2020). "Caspase-1 and caspase-8 are required for IL-1β processing and secretion during this fungal infection." (PMID 31425553, 2019). "Other recent reports have demonstrated novel caspase-8 inflammasome activation in response to bacterial or fungal infection." (PMID 26224068, 2015). "Our observation showed that non-cannonical caspase-8 inflammasome was significantly activated in ischemic retinal tissue, which could also been newly found in fungal infection." (PMID 26224068, 2015).
gastric tumor (5 papers, 2018 to 2023). "Among these, 2 genes were affected by high-confidence LoF germline variants: FANCG (germline splice site variant, c.307 + 1G > C) in gastric tumor of dou_004 and CASP8 (germline deletion variant, c.658_659del) in colorectal tumor of dou_010." (PMID 34285288, 2021). "For example, harmaline, a classic indole alkaloid, has been explored for its ability to inhibit gastric tumor growth both in vitro and in vivo upregulating Fas/FasL expression and further activating caspase-8/-3." (PMID 38053135, 2023). "Also, similar numbers of apoptotic cleaved Caspase-3+ and cleaved Caspase-8+ cells were observed in 3mo and 6mo gp130F/F and gp130F/F:Nlrp3-/- mouse gastric tumors." (PMID 35299732, 2022).